SHBG (sex hormone binding globulin)
Diseases named in the same sentence as SHBG in open-access papers (continued):
Sharing a sentence is not in itself a finding about the gene and the disease.
Obesity (continued). "In women, an obesity-related decrease in SHBG is accompanied by a higher free T. This is in contrast to obese men, in whom a decrease in SHBG is accompanied by a decrease in total T, whereas free T remains normal or slightly decreases." (PMID 30275830, 2018). "In these studies, influence of obesity on the relationship between SHBG and atherosclerosis has also been underestimated." (PMID 29213285, 2017). "Factors that are known to decrease SHBG concentration include androgens (including anabolic steroid use), obesity, hyperinsulinism, metabolic syndrome, T2DM, hypothyroidism, glucocorticoids and atorvastatin treatment." (PMID 28980739, 2017). "We expected loss of significance when adjusting for waist circumference, since SHBG is correlated with obesity with decreased concentrations in adiposity." (PMID 28498873, 2017). "Conversely, obesity-induced hyperinsulinemia inhibited hepatic SHBG synthesis, which further led to a reduction in testicular androgen synthesis." (PMID 27270834, 2016). "Testosterone and its binding protein sex hormone binding globulin (SHBG) are also decreased in obesity." (PMID 27584019, 2016). "Our findings are consistent with the known inter-relationship of obesity, physical activity, insulin, sex hormones and SHBG." (PMID 23113944, 2012). "Men with obesity, metabolic syndrome, and type-2 diabetes have low total and free testosterone and low sex hormone-binding globulin (SHBG)." (PMID 22505891, 2012). "One is a classic estrogen-dependent mechanism, in which obesity contributes to lower serum levels of sex hormone-binding globulin and higher circulating levels of endogenous estrogen." (PMID 23350064, 2012). "In fact, female patients with upper body obesity usually have lower SHBG concentrations in comparison with their age and weight-matched counterparts with lower body obesity." (PMID 25246891, 2012). "Some have argued that many free testosterone concentration measurements use a tracer analogue method that is affected by SHBG (sex hormone-binding globulin) levels, which in turn are decreased by obesity and high insulin concentrations." (PMID 19433001, 2009). "The patients enrolled from the infertility clinic seem to have lower body weight and higher SHBG than the patients enrolled from the endocrine/obesity." (PMID 16603055, 2006). "Obesity has also been shown to increase testosterone and leptin levels, and to depress sex-hormone-binding globulin concentrations." (PMID 16168130, 2005). "Recently, reports have increasingly explored the complex regulatory mechanisms of SHBG in endocrine functions and its role in metabolic syndromes, e.g., obesity, diabetes mellitus, and NAFLD, highlighting its potential as a diagnostic marker and therapeutic target." (PMID 40625923, 2025). "Children in the MAFLD group had lower levels of HDL[(1.05 ± 0.21)mmol/L vs.(1.16 ± 0.26)mmol/L], testosterone [42.41(30.33,143.28)ng/dl vs.125.41(23.41,221.57)ng/dl], and SHBG[13.20(9.10,17.30)nmol/l vs.19.60(13.50,29.85)nmol/l] compared to the simple obesity group (P<0.05)." (PMID 39980852, 2025). "MR analysis revealed that genetically increased Bio-T was associated with lower obesity risk in males, while SHBG showed a negative correlation with visceral and waist obesity." (PMID 41310874, 2025). "OSA is highly prevalent in men with obesity and is consistently associated with lower concentrations of serum testosterone and SHBG compared to men without OSA." (PMID 40052430, 2025). "However, levels of high-density lipoprotein cholesterol (HDL), testosterone, and SHBG were lower in the MAFLD group than in the simple obesity group." (PMID 39980852, 2025). "However, the interpretation of FAI values remains challenging due to the complex interplay between SHBG and factors such as hyperinsulinemia, obesity, diabetes, and hypothyroidism." (PMID 40861046, 2025).
Obesity (continued). "The consequent estradiol surge amplifies negative feedback on the HPG axis, while obesity-associated hyperinsulinemia reduces sex hormone-binding globulin (SHBG), thereby enhancing free testosterone availability for aromatization." (PMID 40292466, 2025). "The fact that peak LH levels were lower as the degree of obesity increased, even though E2 levels remained unchanged, suggested mechanisms such as insulin and leptin resistance, decreased SHBG, and elevated androgen levels in obese individuals, independent of sex steroids." (PMID 40095159, 2025). "There is a tendency to higher SHBG levels among individuals with African-American origin, including prepubertal boys, teenage girls with overweight or obesity and PCOS, glucose-intolerant post-menopausal women, and pre- and peri-menopausal African-American women than the general population." (PMID 40863113, 2025). "Studies show lower SHBG levels in boys with obesity versus normal-weight peers." (PMID 40863113, 2025). "The mediating effect of SHBG in the association between sex and glucose homeostasis, independent of confounders such as age, obesity, and testosterone level, has also been recently reported." (PMID 40217583, 2025). "However, a three-week exposure to KB from a KD results in an increase in SHBG in men and women with obesity as well as it lowers free testosterone and estradiol for men and women." (PMID 39139216, 2024). "In addition, the level of SHBG and SHBG-related sex hormones (androgens and estrogens) correlates significantly with BMI (obesity): Sex hormones have positive correlations with BMI (obesity) and are SHBG-negative." (PMID 38672173, 2024). "Experimental studies and a small cross-sectional study recently found that hepatic de novo lipogenesis might be involved in the downregulation of SHBG synthesis and obesity at least in women." (PMID 38238336, 2024). "The differences in the associations nature of rs10454142 PPP1R21, correlated with the SHBG level in the organism, with BC in women, depending on the obesity presence/absence, may be based on the following mechanisms." (PMID 38672173, 2024). "We found that the BC-risk effect correlated by GWAS with the SHBG-level polymorphism rs10454142 PPP1R21 depends on the presence/absence of obesity." (PMID 38672173, 2024). "However, most of the effect of maternal pre-pregnancy obesity on lower SHBG was mediated by the sons’ own fat mass (indirect effect: −11% (95% CI: −18%; −4%)) and the sons’ own BMI (indirect effect: −13% (95% CI: −20%; −5%))." (PMID 37935951, 2024). "Obesity is negatively correlated with TT, LH, and SHBG, and affects male-factor infertility." (PMID 38991999, 2024). "Men with obesity exhibit reduced levels of testosterone, and sex hormone-binding globulin (SHBG)." (PMID 38524635, 2024). "Furthermore, obesity can induce a decrease in SHBG levels through mechanisms such as insulin resistance and proinflammatory cytokines." (PMID 39224565, 2024). "At the same time, physical activity may delay puberty by reducing the synthesis of sex hormones by reducing obesity, or by decreasing insulin levels, increasing sex hormone-binding globulin levels, and decreasing estradiol bioavailability." (PMID 38719835, 2024). "In control women, HA is often attributed to obesity, as abdominal fat distribution could reduce SHBG synthesis and contribute to a higher level of FAI, a bioactive androgen form." (PMID 38256617, 2024). "Given the association between obesity and increased levels of various inflammatory markers, the presence of chronic low-grade inflammation in obesity can impact the production of testosterone and Sex Hormone-Binding Globulin (SHBG) through the hypothalamic-pituitary-gonadal axis." (PMID 38633753, 2024). "Specifically, Estradiol is positively correlated with obesity, whereas TT and SHBG exhibit negative associations." (PMID 38524635, 2024).
Obesity (continued). "Specifically, several studies have demonstrated a relationship between measures of obesity and testosterone, with plasma total testosterone, free testosterone, and SHBG levels negatively correlating with WC, and BMI and WC associated with testosterone deficiency in males with diabetes." (PMID 38915014, 2024). "Hepatic steatosis is associated with lower serum levels of SHBG (likely mediated through the effects of obesity), with a negative correlation between serum SHBG levels and IR." (PMID 37367914, 2023). "This risk is further increased by a reduction in SHBG in the liver of individuals with obesity and an increase in the concentration of non-SHBG-bound estradiol (E2, the most abundant and active estrogen)." (PMID 36755926, 2023). "The etiology of MOSH is likely multifactorial, including reduced levels of SHBG in obesity, increased aromatase activity, and production of adipocytokines and gut-derived endotoxins that impair kisspeptin signaling in the hypothalamus (and thus GnRH secretion)." (PMID 37344792, 2023). "Women with obesity may have increased peripheral availability of estrogen due to low sex hormone-binding globulin and androgenic aromatization to estrogen in adipose tissue." (PMID 37033532, 2023). "In another study, lower SHBG levels have been strongly correlated with increased adipogenesis, however in liver tissue of patients with obesity and metabolic syndrome, providing a strong evidence for the potential regulatory effect of SHBG towards adipogenesis." (PMID 38146533, 2023). "Interestingly, db/db mice with overexpressed SHBG were resistant to obesity development, and fatty liver or hepatosteatosis." (PMID 37402098, 2023). "The cause of this phenomenon in general obesity and non-central obesity was attributed to increased testosterone concentration and decreased concentration of SHBG (sex hormone-binding globulin) and total estrogen." (PMID 37725283, 2023). "Marked SHBG elevations leading to misleadingly normal or even high total testosterone are relatively uncommon, whereas pseudohypogonadism in men with diabetes and/or obesity is very common." (PMID 36995891, 2023). "In conclusion, we have reported that age, obesity, prolonged menstrual cycle, decreased SHBG, and dyslipidemia may affect EH in PCOS, and hyperandrogenism may be an important cause of EH in such patients." (PMID 37149578, 2023). "Both SHBG and FSH jointly mediate the associations between overweight/obesity and hyperglycemia." (PMID 36767197, 2023). "In the female patient population, a correlation could be found in the younger patient population due to the increased testosterone concentration and decreased concentration of SHBG (sex hormone-binding globulin) and total estrogen in obesity." (PMID 37725283, 2023). "There is a negative correlation between BMI and SHBG, and the main cause of lower TT in obesity is lower SHBG." (PMID 38089610, 2023). "Additionally, the extra visceral adipose changes the hormonal milieu in males with obesity, thereby decreasing the SHBG level, free and total T, and inhibin B, and increasing T conversion into E2 because of higher aromatase activity." (PMID 37700299, 2023). "SHBG is synthesised in hepatocytes of the liver A variable serum SHBG concentration is a source of the marked heterogeneity of serum testosterone concentrations among men with obesity." (PMID 35834069, 2022). "Women with PCOS typically have low serum SHBG levels owing to IR and obesity, thus resulting in high levels of bioavailable active free testosterone (FT), leading to higher rates of menstrual disorders, ovarian cysts, hypo-ovulation, infertility, and hirsutism." (PMID 36060969, 2022). "In women, higher BioT was associated with obesity, upper-body fat distribution, and low HDL-cholesterol although, based on analyses modelling the sex hormone-binding globulin-independent effects of BioT, the last two associations might be indirect." (PMID 35049520, 2022).
Obesity (continued). "Our findings indicate that screening of some phthalates may be critical for women with obesity, particularly those with low SHBG levels." (PMID 36149653, 2022). "This cross-sectional study uses data from the National Health and Examination Survey to evaluate the association between exposure to common phthalate metabolites with total testosterone levels, sex hormone-binding globulin levels, obesity, and metabolic syndrome among women." (PMID 36149653, 2022). "Additionally, obesity reduces the production of sex hormone binding globulin (SHBG), which leads to increased circulating levels of free estrogen." (PMID 35612669, 2022). "Youth with obesity have lower SHBG than those with normal weight." (PMID 35684072, 2022). "On the other hand, high plasma levels of IL1β, which is a type of pro-inflammatory cytokine mainly produced by macrophages, may lead to decreased hepatic expression of sex hormone-binding globulin (SHBG) in patients with obesity." (PMID 36065220, 2022). "Our results suggest that plasma adiponectin levels may play a more important role than TNFα in influencing plasma SHBG levels in our prepubertal population with obesity." (PMID 33689083, 2021). "This is of importance since TNFα levels could be an important factor downregulating SHBG production during early stages of obesity development, but once children reach a certain point of inflammation, TNFα plasma levels may not influence SHBG production." (PMID 33689083, 2021). "Additionally, SHBG overexpression also abolishes the increase in insulin, leptin, and resistin and protects against high-fat diet-induced obesity." (PMID 34335746, 2021). "Of the 11 obesity-related circulating biomarkers examined in MEC-APS participants, the T allele of rs73449607 was associated with a 1.25-fold increase (Beta = 0.22; P = 1.2x10-4) in geometric mean for sex hormone binding globulin (SHBG)." (PMID 34329319, 2021). "Low plasma SHBG levels are also present in adult subjects with obesity." (PMID 33689083, 2021). "SHBG levels can be low due to obesity, which is often present in patients with PWS." (PMID 34640379, 2021). "The association between rs73449607 and SHBG seemed to be independent of obesity since the effect estimate and P-value remained similar with (Beta = 0.09; P = 3.8x10-4) and without (Beta = 0.11; P = 3.3x10-5) adjustment for total fat mass." (PMID 34329319, 2021). "Considering BMI was markedly low in the LADA group, our results might be explained by the fact that the effects of obesity on testosterone are more substantial than the effects of SHBG on testosterone in diabetic men." (PMID 34135863, 2021). "Furthermore, SHBG was strongly associated with both insulin sensitivity (HOMA-IR and WBISI) and insulin secretory (IGI) indexes in children with obesity." (PMID 33689083, 2021). "A strong independent association between SHBG, FAI, and cardiovascular disease risk factors (i.e. obesity, insulin, glucose, and HDL levels, DBP, inflammatory markers) has been previously reported in peri- and premenopausal women of the large SWAN (Study of Women across the Nation) study." (PMID 34089497, 2021). "Nevertheless, we postulate that the relationship between DNL and serum SHBG in women is of particular interest as it may provide a mechanistic link between obesity, more specifically hepatic fat accumulation and polycystic ovary syndrome (PCOS)." (PMID 33715205, 2021). "Previous studies have shown that obesity could aggravate low-grade inflammation, resulting in low levels of SHBG and testosterone." (PMID 34135863, 2021). "This higher incidence of cutaneous manifestations in the obese group could be due to the fact that obesity results in an increase in the androgens and a decrease in sex hormone-binding globulin (SHBG) levels, thus increasing free androgen level." (PMID 35106232, 2021). "A study of 84 children with obesity in Taiwan showed a positive correlation between SHBG and HDL-C." (PMID 33291623, 2020).
Obesity (continued). "Obesity has a crucial impact on testosterone levels in both sexes, which might be explained by alterations in the synthesis of SHBG." (PMID 32535783, 2020). "In our study, we successfully established a rat model of PCOS with the characteristics of polycystic ovaries, obesity, irregular estrous cyclicity, hyperandrogenism, increased plasma insulin levels, decreased plasma SHBG levels, and increased LH concentrations." (PMID 32733580, 2020). "Decreased SHBG synthesis in the liver is found in men and women with obesity." (PMID 32535783, 2020). "The fact that the SHBG levels increased while estradiol decreased after bariatric surgery led the authors to conclude that inhibitory influences arising from adipose tissue dominate the picture in severe obesity." (PMID 32326591, 2020). "Another study evaluated 106 young women with PCOS and found low levels of SHBG associated with low levels of HDL-Cholesterol but independent of obesity." (PMID 33139661, 2020). "Low levels of SHBG are commonly found in patients with obesity or type 2 diabetes mellitus." (PMID 31817436, 2019). "We aimed to study the SHBG polymorphism rs1799941 in a cohort of young non-diabetic obese males to unravel the possible implication of this polymorphism in obesity-related hypogonadism." (PMID 31370189, 2019). "A major limitation of our research can be the lack of SHBG for calculation because it is well known that obesity and MS are associated with the reduction of SHBG levels." (PMID 29547878, 2018). "SHBG is reduced in pregnant women with obesity and gestational diabetes." (PMID 30321217, 2018). "Other hypotheses about the acceleration of puberty by obesity involve insulin-like growth factor, insulin, and adiponectin, which may alter the expression of sex hormone-binding globulin." (PMID 29321542, 2018). "Current evidence suggests that the causative relationship between the often low testosterone and type 2 DM might be bidirectional or even multidirectional and interrelated with obesity, MetS, SHBG, and other factors." (PMID 30057912, 2018). "Sex-related hormones such as estradiol and SHBG were significantly correlated with asprosin, which could confirm the notion that overweight/obesity confers IR and then worsens the reproductive and metabolic features of PCOS." (PMID 30524197, 2018). "Meanwhile, obesity has been thought to be a major determinant of circulating SHBG levels." (PMID 29213285, 2017). "Girls with obesity exhibit increased total testosterone production and reduced hepatic sex hormone binding globulin (SHBG) production, and a decrease in the levels of SHBG could result in increased sex steroid bioavailability." (PMID 27215137, 2016). "In conclusion, evidence is accumulating that low SHBG levels are an indicator of IR, and SHBG may be an easy-to-measure and clinically useful biomarker for the early identification of children who are destined to develop obesity-related chronic diseases." (PMID 26761949, 2016). "We did not evaluate a variety of other hormones known to link obesity to gonadotropin secretion, such as insulin, SHBG, and testosterone; as a result, we cannot prove causality." (PMID 27215137, 2016). "In this regard, obesity may contribute to low total testosterone levels that can be explained at least partially by lower sex hormone-binding globulin (SHBG) in obese men." (PMID 26419465, 2015). "However, the clinical usefulness of SHBG as a marker of BPH risk seems uncertain, because its serum concentration, like testosterone, is greatly influenced by aging and coexisting obesity." (PMID 26516352, 2015). "Obesity is related to the increased peripheral conversion of androgenic precursors to estradiol due to increased aromatase enzyme activity from large amounts of adipose tissue and is also related to decreased sex hormone-binding globulin." (PMID 26546331, 2015).